CCL2 (C-C motif chemokine ligand 2)
Diseases named in the same sentence as CCL2 in open-access papers (continued):
Sharing a sentence is not in itself a finding about the gene and the disease.
tumor (continued). "While some reports imply that CCL2 can slow tumor progression and metastasis, data from multiple laboratories indicate that inhibiting CCL2 will alter the tumor microenvironment and antagonize tumor growth." (PMID 28143493, 2017). "Together suggest that CCL2 secreted by MSCs-entrained IRISOE TNBC tumor cells induces expression of its own receptor CCR2 on the surface of the low expressing THP1-macrophages." (PMID 29262555, 2017). "Next, we investigated the biological effect of CCL2 secreted from IRISOE tumor cells on macrophages." (PMID 29262555, 2017). "This disparity is likely because the CCL2 produced by the tumor cells was taken up by the neutrophils." (PMID 28143493, 2017). "CCL2 has been reported to recruit myeloid-derived suppressor cells and pro-tumorigenic macrophages into the tumor microenvironment, to promote the invasive and metastatic properties of solid tumors." (PMID 28143493, 2017). "Undoubtedly, the inhibition of CCL2 with Bindarit reduced macrophage recruitment which suppressed tumor growth." (PMID 29450136, 2017). "We cover fundamental molecular players in the tumor microenvironment including extra- (CCL2, CSF-1, CXCL12, IL-4, IL-13, semaphorins, WNT5A, and WNT7B) and intracellular signals." (PMID 28197019, 2017). "TAMS, upon arrival, can then lead to even more release of promoting cytokines: TGF-beta, MMPs, VEGF, CM/M-CSF, CCL 17, IL-13 and CCL2 which secure pro-angiogenic tumor processes." (PMID 28441391, 2017). "Reactive oxygen species (ROS) produced by MDSCs can also lead to nitration of CCL2 (N-CCL2), which has been found to contribute to infiltrated T-cell exclusion, trapping T lymphocytes in the stroma that surrounds the tumour." (PMID 28193698, 2017). "CCL2 secreted by endothelial cells has been found to stimulate angiogenesis, and ultimately support tumor progression." (PMID 28143493, 2017). "Together suggest that IL-1β secreted by IRISOE tumor cells activates MSCs in a paracrine fashion to secrete CXCL1, which also in a paracrine fashion activates IRISOE tumor cells to secrete CCL2." (PMID 29262555, 2017). "While CCL2 recruits and activates pro-tumor macrophages, it is also reported to enhance neutrophil-mediated anti-tumor activity." (PMID 28143493, 2017). "The results showed that several genes were highly expressed in tumor, including Cxcl2, Ccl2, Ccl3, Ccl4, and Ccl5." (PMID 28432279, 2017). "This paracrine-induced senescence has also been shown recently for TGF-β, VEGF and CCL2 suggesting that this is a general mechanism for senescence propagation involving not only tumour cells but also surrounding stromal cells." (PMID 28472950, 2017). "The recruitment and accumulation of TAMs into tumors are initiated by macrophage chemoattractants [e.g., CCL2/monocyte chemoattractant protein 1 (MCP-1), colony-stimulating factor 1 (CSF-1)] and it is well established that TAMs drive tumor progression." (PMID 28769933, 2017). "Together suggest that IL-1β secreted by IRISOE tumor cells recruits MSC into tumors’ aggressiveness niche, activates them to secrete CXCL1, which entrains IRISOE tumor cells to secrete higher local and systemic levels of CCL2 and VEGF, in vivo." (PMID 29262555, 2017). "Another HCMV gene implicated in tumor development is US28, which encodes a functional chemokine receptor that binds several human chemokines, including CCL2/MCP-1, CCL5/Rantes, and CX3CL1/Fractalkine." (PMID 28228690, 2017). "Adipocytes induce CCL-2 and M-CSF expression in B16F10s, which increases the number of M2-MΦs in the tumor." (PMID 28410190, 2017). "Together suggest that at least in culture, CCL2 secreted by MSCs-entrained IRISOE TNBC tumor cells recruits THP1-macrophages to the vicinity of tumor cells, most likely through inducing expression of CCR2 on naïve THP1-macrophages surface." (PMID 29262555, 2017).
tumor (continued). "The same report also demonstrated that neutrophils isolated from tumor bearing mice and patients possess higher levels of CCL2, which contributed to their killing ability." (PMID 28143493, 2017). "Deletion of one of the CCR2 ligands, CCL2, in the host has been reported to diminish both cancer cell metastatic capacity and primary tumor growth." (PMID 29170400, 2017). "The stromal microenvironment of ER+ and ER− tumours is markedly different, including the higher expression of MDSC-recruiting CCL2 in ER− tumours." (PMID 28193698, 2017). "Plasma CCL2 upregulation in the peripheral blood (PB) and BM was reported in AML patients, and CCL2 expression levels in the tumor microenvironment were elevated in MDS as well as AML." (PMID 29179486, 2017). "For example, CCL2 and IL-6 were found to contribute to the survival of CD11b+ myeloid monocytes recruited to the tumor microenvironment and skew the phenotype toward tumor-promoting CD14+/CD206+ M2-type macrophages." (PMID 28948005, 2017). "CCL2 overexpression in tumor is correlated with macrophage infiltration and poor prognosis in human cancers." (PMID 28769933, 2017). "CCL2 is a chemokine produced by cancer cells that is responsible for the recruitment of monocytes at the tumor site." (PMID 28769933, 2017). "A series of chemoattractants, chemokines, orchestrate the recruitment of monocytes/macrophages; the chemokine CCL2 (also known as MCP-1) was first discovered as a tumor-derived chemotactic factor which recruits these cells to tumor tissues." (PMID 28197019, 2017). "Only in multiparous aged mice, e.g., animals exposed to P4 during pregnancies early in life, did our results show lower CCL2 levels in response to tumor induction." (PMID 28966800, 2017). "p = 0.058) and we observed enhanced tumor cell viability in co-cultures of naïve neutrophils treated with CCL2 (adj." (PMID 28143493, 2017). "Stem cells can also secret factors, such as CCL2/MCP-1, and physically interact with tumor cells, changing co-cultured tumor cell phenotypes and exerting intrinsic antitumor effects." (PMID 29088907, 2017). "When CCL2 was added to co-cultures of naive neutrophils isolated from non-tumor bearing BALB/c mice and 4 T1 cells, tumor cell killing by neutrophils was increased." (PMID 28143493, 2017). "Combined, our data suggest that biopsy-induced tumor progression is induced by a CCL-2 mediated recruitment of macrophages." (PMID 28790339, 2017). "We observed that macrophages differentiated with CM polarized toward an anti-inflammatory, tumor-tolerant phenotype showing increased expression of Arginase 1, Ccl2, and Vegf." (PMID 29167669, 2017). "Previous work has shown that in PAFR KO animals with Ehrlich tumor ascites, elevated levels of CXCL2 and CCL2 chemokines controlled the recruitment of myeloid cells to the tumor." (PMID 29445756, 2017). "Among the chemotactic factors, chemokine (C-C Motif) ligand 2 (CCL2) is considered to be a key player in the recruitment of monocytes to the tumor, and the CCL2-CCR2 axis has been proposed as a new therapeutic target." (PMID 28220123, 2017). "Ti-Treg and Ti-Teff cells are the main subsets of CD4+CCR4+ T cells, and they always are recruited into the tumor microenvironment via the CCL2/CCR4 axis." (PMID 29312296, 2017). "After tumor inoculation, the expression of mRNA and protein levels for CCL2 and CCR2 in tumor group were significantly increased compared to the sham group (p < 0.01)." (PMID 28587280, 2017). "M-MDSC and monocytes are recruited to primary tumour sites and metastatic sites by chemokines secreted by tumour cells, most commonly CCL2 and CCL5, which function to regulate monocyte chemotaxis." (PMID 28193698, 2017). "CCL2 has also been shown to mediate its tumor-supportive ability by acting as a potent chemoattractant for MDSCs and unpolarized monocytes while contributing to polarization of monocytes to MDSCs by increasing their CD206 expression." (PMID 28212753, 2017).
tumor (continued). "It has been shown that CCL2 plays an important role in macrophage accumulation at the tumor site through evidence indicating that tumor-derived CCL2 levels were correlated with the abundance of TAMs in several types of cancers." (PMID 28039457, 2017). "TAMs and Treg cells are also recruited to the pre-metastatic niche by primary tumor-derived fibrin clots, and by CCL2 and CCL22, respectively, and these cells promote future metastasis." (PMID 29450136, 2017). "The versatile roles of CCL2 in both promotion of tumor progression/metastasis and education of immunocyte make the CCL2-signaling a dramatic therapeutic target for tumor treatment." (PMID 28533507, 2017). "Using our IVM tools, we show that biopsy in brain tumors of mice induces a CCL-2-dependent recruitment of macrophages that potentiates tumor cell migration and proliferation." (PMID 28790339, 2017). "Tumor cell derived inflammatory cytokines and growth factors including colony stimulating factor (CSF-1), GM-CSF, CCL2 and other factors which participate in tumor progression." (PMID 29137220, 2017). "Collectively, endogenous TRAIL/TRAIL-R-mediated CCL2 secretion promotes accumulation of tumor-supportive immune cells in the cancer microenvironment, thereby revealing a tumor-supportive immune-modulatory role of the TRAIL/TRAIL-R system in cancer biology." (PMID 28212753, 2017). "For instance, despite inhibition of CCL2 or CCR2 within the tumor microenvironment was indicated to be beneficial in inhibiting metastasis." (PMID 29197379, 2017). "RT also promotes macrophage infiltration, from the peritumoral environment to the tumor site, in a CCL2 dependent way." (PMID 28769933, 2017). "CXCL1 functions to entrain IRISOE TNBC tumor cells to secrete higher levels of CCL2 and VEGF (steps 3)." (PMID 29262555, 2017). "In the tumor microenvironment, TAMs originate from the monocyte lineage through the action of cytokines, e.g., chemokine (C-C motif) ligand 2 (CCL2), secreted by stromal cells and cancer cells." (PMID 28178994, 2017). "High number of tumor infiltrating lymphocytes correlate with increased expression of a cluster of chemokines that comprise CCL2 and CXCL10, with CXCL9 and CXCL10 critically involved in the recruitment of effector CD8+ T cells." (PMID 29064427, 2017). "By repeated high-resolution intravital microscopy, we show that biopsy-like injury in GBM induces migration and proliferation of tumor cells through chemokine (C-C motif) ligand 2 (CCL-2)-dependent recruitment of macrophages." (PMID 28790339, 2017). "Here we identify that within the TRAIL secretome, CCL2 fulfils a central function in the formation of a tumor-supportive myeloid compartment that is achieved in vivo via the engagement of CCR2 on host cells." (PMID 28212753, 2017). "There are studies showing that extracellular matrix components, IL-10, chemokines CCL17 and CCL2, and CSF-1 produced by tumor cells drive macrophages toward M2 mode." (PMID 28487844, 2017). "Our study establishes tumor cell-expressed TRAIL-R as a trigger for cancer cells to secrete CCL2, which, in turn, drives accumulation of a pro-tumorigenic immune microenvironment via host cell-expressed CCR2." (PMID 28212753, 2017). "CCL2 induced epithelial mesenchymal transition (EMT) in order to promote tumor metastasis in various cancer types." (PMID 28757590, 2017). "The CCL2 inhibitor bindarit significantly suppresses M2 macrophage recruitment and tumor growth in human melanoma xenografts." (PMID 28467800, 2017). "The inhibition of CCL2/C–C chemokine receptor type 2 or CSF1/CSF1-R pathways by several methods was shown to efficiently induce tumor regression." (PMID 28769933, 2017). "For instance, CAFs secrete CC chemokine ligand 2 (CCL2), which recruits macrophages to the tumor site through binding to its receptor CCR2." (PMID 28467800, 2017).
tumor (continued). "Together suggest that while IRISOE tumor cells secrete low-level CCL2 under normal condition, hypoxia and/or MSCs contact through the IL-1β/CXCL1 circuit exacerbates CCL2 secretion from these cells." (PMID 29262555, 2017). "TNFα evoked release of tumor-promoting chemokines such as CCL2 (MCP-1), CCL5 (RANTES) and CXCL8 (IL-8) trigger infiltration of CCR2/CCR5 receptor bearing leukocyte sub-populations (LSPs) including TAMs, MDSCs, TANs, Tregs, MAMs and CAFs." (PMID 28441391, 2017). "The small molecule inhibitor Bindarit has been reported to be effective in reducing tumor growth and macrophage recruitment in CCL2-positive melanoma." (PMID 28471401, 2017). "Previous studies also showed that CCL2 can regulate tumor progression and metastasis by altering the tumor microenvironment." (PMID 28757590, 2017). "That is, there was no statistically significant change in luminescent signal between the tumor cells plus naïve neutrophils samples and tumor cells plus naïve neutrophils plus CCL2 samples." (PMID 28143493, 2017). "CCR2-driven infiltration of γδT17 cells was consistent with upregulation of its major ligand CCL2 in tumours." (PMID 28580944, 2017). "In these experiments, naïve and TEN neutrophils produced very low levels of murine CCL2 (with the exception of 2/5 isolates of 4 T1 TEN), while tumor cells tended to secrete much higher levels of CCL2." (PMID 28143493, 2017). "The capacity of CCL2 to attract tumor-promoting and immunosuppressive cells or their precursors provides a strong rationale for attempting to therapeutically reduce CCL2 levels in the setting of established neoplasms." (PMID 28143493, 2017). "In the other 4T1 cells implanted tumor model, an anti-CCL2 monoclonal antibody was administered intraperitoneally, resulting inhibit the growth of primary malignant lesions and reduce the number of pulmonary metastatic spread in BALB/c mice." (PMID 26794215, 2016). "Despite its major role in regulating the immune response by recruiting monocytes, memory T cells and dendritic cells to sites of inflammation, CCL2 also possesses tumor-promoting potential as demonstrated in several mouse models." (PMID 26684239, 2016). "Our data indicate that CCL2 gene silencing significantly remodeled the microenvironment to suppress tumor progression." (PMID 27283985, 2016). "Our data showed that treatment with embelin led to a significant impairment in the expression of CSF1, CCL2 and GM-CSF in tumor tissues whereas only very mild apoptosis in macrophages was detected." (PMID 26799669, 2016). "The tumor-promoting effects of CCL2 have been ascribed to the recruitment of monocytes, which leads to a profuse vascular network." (PMID 26684239, 2016). "Although the highly aggressive behavior of tumors in Ccr2-/- mice appears to be a consequence of more than just loss of CCR2 signaling, the tumors in these mice provided a clue about a mechanism by which intact CCL2/CCR2 signaling influences tumor progression." (PMID 27820834, 2016). "In agreement with a tumor-promoting role, higher CCL2 plasma levels after one month of therapy were detected in patients with short-term responses to BRAFi treatment compared with the levels in long-term responders." (PMID 26684239, 2016). "To find evidence for such changes, we analyzed gene expression profiles of circulating monocytes isolated from tumor-free wild type, Ccl2-/-, and Ccr2-/- mice." (PMID 27820834, 2016). "CCL2 regulates the infiltration of monocytes/macrophages and is reflected in tumor sites; in addition, HIF-1α is a critical transcriptional factor." (PMID 27271610, 2016). "Recent observations that CCL2 overexpression in tumor cells increased metastasis are in accordance with our findings." (PMID 26701209, 2016). "Studies had proposed a dual role of CCL2 on tumor growth, and CCL2 can be protective in some tumor models but destructive in others." (PMID 27191744, 2016).
tumor (continued). "Together, our data showed the infiltrated mast cells in the tumor microenvironment enhance BCa metastasis via stimulating ERβ/CCL2/CCR2 EMT/MMP9 signals both in vitro and in vivo." (PMID 26556868, 2016). "Macrophage recruitment in tumor microenvironment usually resulted from the expression of CCL2 by tumor cells." (PMID 27608847, 2016). "In breast tumors, TAMs are recruited to pulmonary metastases by CCL2 and enhance extravasation, seeding, and persistent growth of tumor cells in part via expression of VEGF." (PMID 27975071, 2016). "The VEGFA and CCL2 mainly released by fibroblasts in the tumor microenvironment are responsible for tumor angiogenesis and TAMs accumulation, thereby boosting tumor growth and metastasis." (PMID 27541266, 2016). "Paradoxically, we observed that targeted disruption of Ccr2, which encodes the only high affinity signaling receptor for CCL2, promotes HER2/neu-driven tumor growth and shortens overall survival." (PMID 27820834, 2016). "In this study, we first showed that CCL2 expression was correlated with higher clinical stage, worse tumor grade, and poor prognosis in ccRCC patients." (PMID 27666332, 2016). "This correlated with a reduction of macrophage recruitment to the tumor tissue, likely due to diminished CCL2 production by tumor cells with abrogated IL-33/ST2 signaling." (PMID 28119694, 2016). "Recently, it was revealed that the levels of VEGF and TNF-α in serum of tumor bearing mice were higher than the control group after implanting 4T1 cells for 10 days, but the CCL2 level was increased quickly after implantation." (PMID 26794215, 2016). "A variety of chemokines, like CCL2 and CCL5, have been detected in neoplastic tissues and associated with tumor associated immune cells formation and recruitment." (PMID 26790618, 2016). "Il17−/− mice had reduced lung tumor numbers, as well as reduced tumor cell proliferation, angiogenesis, myeloid cell recruitment and expression of pro-inflammatory mediators (Il6, Cxcl2, Ccl2, Arg1, Csf3, Mmp7, Mmp12 and Mmp13) compared to Il17+/+ mice." (PMID 27784305, 2016). "Blockade of CCL2/CCR2 is associated with reduced influx of inflammatory monocytes and tumour associated macrophages into HCC microenvironment." (PMID 27270308, 2016). "CCL2 synthesized by a tumor and stroma also triggers a prometastatic chemokine cascade (involving CCL3 signaling via CCR1) that is required for efficient metastasis." (PMID 27975071, 2016). "Direct CCL2 targeting or the inhibition of its production has been reported to decrease the frequency of tumor-infiltrating MDSCs, to restrict neoangiogenesis and to suppress the growth of transplantable tumors." (PMID 27827871, 2016). "In vitro, the RG7356-mediated disruption of the tumor microenvironment triggers the release of specific chemo-attractants (e.g. CCL2) that recruit and activate macrophages, leading to the phagocytosis of RG7356-opsonized tumor cells (Roche internal data)." (PMID 27081038, 2016). "More importantly, we demonstrated that systemic delivery of anti-VEGFA/CCL2 or pre-miR-1, pre-miR-206 and anti-miR-31 dramatically decreased tumor angiogenesis, TAMs accumulation, tumor growth and lung metastasis." (PMID 27541266, 2016). "According to the cutoff value, 56.0% (150/269) and 63.8% (171/268) of the tumor tissues were scored as high CCL2 and high CCR2 expression, respectively." (PMID 27409666, 2016). "In our study, we showed that siRNA delivery effectively reduced CCL2 expression in the primary tumors to levels normally found in normal mammary tissues, and suppressed tumor progression." (PMID 27283985, 2016). "Our previous study has identified that the main ligand for CCR2, CCL2, was highly expressed in gastric tumor tissues, and correlated with tumor progression." (PMID 26992207, 2016). "In fact, the inhibition or neutralization of CCL2 using drugs or specific antibodies reduced tumor growth." (PMID 26684239, 2016).